YTHDF2 (YTH N6-methyladenosine RNA binding protein F2)
Diseases named in the same sentence as YTHDF2 in open-access papers (continued):
Sharing a sentence is not in itself a finding about the gene and the disease.
tumor (continued). "Low expression of YTHDF2 in these cancers was found to be linked to poor OS in patients, as well as increased tumor size, TNM stage, lymph node, and distant metastasis." (PMID 35382893, 2022). "To further explore the mechanism underlying YTHDF2 mediated tumor development and progression, we carried out a series of pathway enrichment analyses on YTHDF2 interacting proteins and related genes based on STRING and GEPIA2." (PMID 36120577, 2022). "In contrast, METTL3 regulates tumor growth by cooperating with YTHDF2 to modify tumor-associated neutrophils (TANs) infiltration and performs a key tumor suppressor role in papillary thyroid carcinoma." (PMID 36386128, 2022). "In order to identify the tumor immune microenvironment associated with the expression of YTHDF1 or YTHDF2, the association between such expression and immune checkpoints other than PD-1/PD-L1 was investigated." (PMID 36479088, 2022). "YTHDF2 is linked to multiple functions of human cancer cells and acts as an oncogene or tumor suppressor gene in different cancers." (PMID 35382893, 2022). "The correlation of YTHDF2 expression with tumor mutation burden, microsatellite instability and mismatch repair was also detected in most of the tumor types." (PMID 36120577, 2022). "We also investigated the association of YTHDF2 expression with prognosis, immune infiltration, tumor microenvironment, immune checkpoints and chemokines." (PMID 36120577, 2022). "So far, the existing evidence is insufficient to conclude a consistent pathogenic role of YTHDF2 in tumor development and progression, let alone its functional mechanism in regulating the immune microenvironment and modulating therapeutic responses." (PMID 36120577, 2022). "Other studies have suggested the potential of YTHDF1 and YTHDF2 as new prognostic factors and drug targets associated with the tumor immune microenvironment of NSCLC." (PMID 35924072, 2022). "Multivariate analysis showed that YTHDF2 expression was an independent risk factor for tumor progression (TCGA-KIRC cohort: OS, HR = 0.615, 95% CI: 0.405–0.934; p < 0.05)." (PMID 34512342, 2021). "Since the expression levels of the four selected genes (KIAA1429, LRPPRC, RBM15B, and YTHDF2) play a crucial role in tumorigenesis and tumour development, we employed them to establish an m6A risk signature model." (PMID 34512165, 2021). "Silencing YTHDF2 expression in human HCC cells can cause tumour inflammation, vascular remodeling and metastasis." (PMID 34246319, 2021). "In the ICGC cohort, KIAA1429, LRPPRC, RBM15B, and YTHDF2 expression levels and the m6A risk score were significantly correlated with tumour grade." (PMID 34512165, 2021). "The differential expression of YTHDF2 mRNA in ccRCC and tumor-adjacent normal tissues and associated with clinicopathological characteristics was also analyzed." (PMID 33102202, 2020). "YTHDF2 had the potential to regulate polarization of tumor-associated macrophages, induce T-cell exhaustion, and activate T-regulatory cells." (PMID 33344502, 2020). "The differential YTHDF2 expression in ccRCC and tumor-adjacent normal tissues and associated with clinicopathological characteristics was analyzed by using mRNA expression data from The Cancer Genome Atlas (TCGA) ccRCC cohort." (PMID 33102202, 2020). "The analysis showed that YTHDF2 expression was associated with tumor purity in 14 cancer types and B cell infiltration levels in 10 cancer types." (PMID 32986017, 2020). "In line with increased nuclear expression in tumor regions, we uncover its association with Ythdf2 gene promoter and transcriptional suppression." (PMID 31735169, 2019). "Additionally, YTHDF2 deficiency suppresses tumor glycolysis, which enhances mitochondrial respiration in CD8+T cells and subsequently stimulates their anti-tumor function." (PMID 41522342, 2026).
tumor (continued). "The YTHDF2 inhibitor DC-Y13-27 enhances the anti-tumor effects of radiotherapy and radio-immunotherapy by mimicking the phenotypic consequences of YTHDF2 loss, which include altered MDSC differentiation, suppressed intra-tumoral trafficking, and attenuated immunosuppressive activity." (PMID 41522342, 2026). "By promoting the degradation of mRNAs encoding certain immune evasion molecules and antigens, YTHDF2 may enhance tumor cell recognition by immune cells and improve their susceptibility to immune-mediated clearance." (PMID 39911396, 2025). "Moreover, YTHDF2 has been implicated in modulating immune cell function within the tumor microenvironment." (PMID 39911396, 2025). "The loss of YTHDF2 in regulatory T (Treg) cells reduces tumor growth in mice." (PMID 41184358, 2025). "Ythdf2 deficiency impairs NK cell anti-tumor and antiviral responses." (PMID 41403953, 2025). "YTHDF2 is associated with tumor progression and immune infiltration in HCC." (PMID 39199296, 2024). "Additionally, the knockdown of YTHDF2 significantly inhibited the proliferation of MM cells, caused cell cycle G1/S cycle arrest in vitro, and suppressed tumor growth in vivo." (PMID 37012388, 2023). "Similarly, the expression of YTHDF2 has been shown to correlate with immune-cell and tumour-associated-macrophage markers and was associated with poor survival in low-grade glioma." (PMID 37444417, 2023). "Thus, YTHDF2 is closely associated with many aspects of tumors by influencing the mRNA stability of tumor suppressors or oncoproteins." (PMID 36870954, 2023). "Furthermore, YTHDF2 is closely associated with the proliferation, apoptosis, invasion, and migration of tumor cells, suggesting its significant role in cancers." (PMID 35382893, 2022). "In addition, the involvement of YTHDF2 in “Spliceosome” and “RNA degradation” were two potential functional mechanisms underlying its influence on tumor progression." (PMID 36120577, 2022). "Finally miR-491-3p was reported to target YTHDF2, a methylation of the N6 position of adenosine (m6A) reader protein, and mitotic arrest deficient-2 (Mad2) to affect tumor cell proliferation." (PMID 33098307, 2021). "Tumor proliferation, apoptosis and angiogenesis were enhanced in the YTHDF2-deficient mouse liver." (PMID 31735169, 2019). "Notably, YTHDF2, in association with m6A‐circRNA, can suppress innate immunity, whereas circRNA acts as an adjuvant inducing activation of antigen‐specific T cells, generation of antibodies and enhancement of anti‐tumour immune responses." (PMID 39135292, 2024). "Moreover, the loss of YTHDF2 led to reduction of tumor burden and lung metastasis in mice." (PMID 37369946, 2023). "However, there are few reports about SNPs in the YTHDF2 gene and tumor risk." (PMID 34970571, 2021). "METTL3 inhibition or knockout affects tumor cell proliferation and tumor growth, with YTHDF2 playing a key role and enhancing antitumor effects in a T-cell-dependent manner, indicating that YTHDF2 is a downstream executor of STM2457’s antitumor effects." (PMID 40678060, 2025). "The bubble plot indicated that about 40% of patients showed notably elevated YTHDF2 expression in tumor tissues." (PMID 41323282, 2025). "YTHDF2, by regulating the expression of inflammatory mediators and immunosuppressive molecules, contributes to immune tolerance and tumor immune evasion." (PMID 41403953, 2025). "Loss of Ythdf2 reprograms TAMs toward an anti-tumor state, enhancing antigen cross-presentation and CD8+ T-cell immunity, thereby restraining tumor growth." (PMID 41403953, 2025). "In DLBCL, Hippo–YAP pathway inactivation via carbohydrate sulfotransferase 11 (CHST11) and KIAA1429/YTHDF2 repression inhibits cell proliferation and tumor growth and induces cell cycle arrest and apoptosis." (PMID 39802639, 2025). "This reduction prevents recognition by the m6A reader YTHDF2, resulting in increased PD-L1 mRNA stability that suppresses T cell cytotoxic activity and facilitates tumor immune evasion." (PMID 40176140, 2025).
tumor (continued). "As an m6A-binding protein, YTHDF2 expression is significantly increased when NK cells are activated by cytokines, tumour cells, or viruses." (PMID 40356909, 2025). "In vitro and in vivo experiments demonstrate that niclosamide, a broad-spectrum anthelmintic, exhibits anti-tumor effects by modulating YTHDF2, expanding its therapeutic applications." (PMID 41323282, 2025). "Following exposure to ionizing radiation, the depletion of YTHDF2 in myeloid cells has been shown to enhance antitumor immunity and reduce tumor radioresistance." (PMID 39987091, 2025). "Through destroying tumor-suppressor mRNAs, histone lactylation promotes the production of YTHDF2, which speeds up the process of carcinogenesis." (PMID 39968078, 2025). "Lactylation enhances YTHDF2 expression and stability, thereby accelerating the degradation of tumor-suppressive mRNAs that contain m6A modifications." (PMID 41583433, 2025). "Researchers have discovered that inhibiting YTHDF2 can reprogram TAMs to an anti-tumor phenotype and enhance their antigen cross-presentation ability to suppress tumor growth." (PMID 40520002, 2025). "A431 xenografts in nude mice revealed that knockdown of YTHDF2 increased tumor growth, whereas forced overexpression of YTHDF2 decreased tumor growth." (PMID 41224760, 2025). "Complementing this, tumor-intrinsic YTHDF2 has been shown to limit expression of the chemokine CX3CL1, thereby restraining macrophage recruitment and shaping the myeloid landscape within tumors." (PMID 41280938, 2025). "Mechanistically, tumor-derived TNF signaling induces YTHDF2 expression, which accelerates degradation of m6A-modified NF-κB negative regulators, maintaining NF-κB activation and Treg function." (PMID 41403953, 2025). "Further research confirmed YTHDF2’s crucial role in promoting tumor cell proliferation and invasion in both in vitro and in vivo settings." (PMID 41323282, 2025). "Immunohistochemical staining further supported this observation, showing significantly increased YTHDF2 staining signals in tumor tissues, with the intensity and distribution of staining indicating expression levels." (PMID 41323282, 2025). "Sh‐YTHDF2 and DNase I increased the production of lipid ROS in tumours and had a superimposed effect." (PMID 39865544, 2025). "This increase in methylation accelerates mRNA decay via YTHDF2, thereby preventing tumor growth and potentially improving responses to anti-PD-1 therapies." (PMID 40176140, 2025). "Conversely, loss of YTHDF2 in tumor cells led to macrophage recruitment via CX3CL1 and enhanced mitochondrial respiration in CD8 + T cells by impairing tumor glycolysis." (PMID 39987091, 2025). "Conditional YTHDF2 deletion in Tregs impairs their function, increases apoptosis, and limits tumor growth, confirming the role of m6A regulation in tumor Tregs." (PMID 40703514, 2025). "Functional rescue experiments showed that reintroduction of miR-126 counteracts the tumor-suppressive effects of YTHDF2 depletion, indicating that the YTHDF2/miR-126 axis represents a critical oncogenic pathway and a potential therapeutic vulnerability in AML." (PMID 41403953, 2025). "In tumor-associated macrophages (TAMs), YTHDF2 is upregulated via the IL-10/STAT3 pathway and suppresses IFN-γ/STAT1 signaling, maintaining a pro-tumor phenotype." (PMID 41403953, 2025). "H&E staining showed that sh‐YTHDF2 and DNase I reduced lung tumour nodules and tumour cells number, and increased necrotic cells number, with a superimposed effect." (PMID 39865544, 2025). "Sh‐YTHDF2 and DNase I inhibited NETs formation in tumours, increased the activity of CD8(+) T cells and inhibited LUAD growth." (PMID 39865544, 2025).
tumor (continued). "YTHDF2 directly binds to and degrades Bambi transcripts in MDSCs in an m6A-dependent manner, thereby affecting both the tumor-infiltrating capacity and suppressive function of MDSCs through the inhibition of TGF-β signaling." (PMID 39987091, 2025). "Extensive studies have reported on the roles and mechanisms of YTHDF1 and YTHDF2 in tumor immune regulation." (PMID 41403953, 2025). "EBRT resulted in pronounced inhibition of tumour growth in Ythdf2-c knock-out mice compared to wild-type mice, assessed by both tumour volume and animal survival." (PMID 40016527, 2025). "Sh‐YTHDF2 and DNase I inhibited NETs formation in tumour, increased CD8(+) T cells activity, and inhibited LUAD growth." (PMID 39865544, 2025). "Further studies revealed that FBW7 triggers the proteasomal degradation of YTHDF2, thereby counteracting its tumour-promoting effect." (PMID 40356909, 2025). "A comparative analysis of YTHDF2 expression in tumor and normal tissues was conducted using the GSE29272 and TCGA_STAD datasets." (PMID 41323282, 2025). "We collected tumor tissues for Western blot detection, and found that niclosamide inhibited the expression of YTHDF2, which indicates that niclosamide suppresses tumor growth as an inhibitor of YTHDF2." (PMID 41323282, 2025). "It has been documented that YTHDF2 can influence CD8+ T cell function by modulating tumor cell glycolysis, consequently affecting tumor progression." (PMID 41323282, 2025). "Conversely, YTHDF2 also functions as a tumour suppressor by hastening the degradation of EGFR transcripts, which in turn curtails HCC growth." (PMID 38239038, 2024). "Combining YTHDF2 siRNA and cisplatin significantly enhanced cisplatin's anti‐tumour effects in chemoresistant ICC PDX models, suggesting new combined therapeutic strategies for ICC." (PMID 39135292, 2024). "Elucidating the regions of YTHDF2 that participate in its oncogenic and tumor‐suppressive roles is needed to further understand the role of YTHDF2 in cancer processes." (PMID 38247171, 2024). "In mouse models, DC-Y13-27 has shown effects similar to Ythdf2 knockout, effectively enhancing the efficacy of IR and the anti-tumor effects of IR combined with PD-L1 antibody treatment." (PMID 39593172, 2024). "Immunohistochemistry (IHC) of clinical samples revealed that YTHDF2 expression increases with tumor grade and correlates positively with PRMT6 expression." (PMID 38637831, 2024). "Loss of ALKBH5 reduces Period Circadian Regulator 1 (PER1) expression in a YTHDF2-dependent manner, promoting tumor migration, invasion, proliferation, and growth." (PMID 39342406, 2024). "The increased tumor size and lung metastatic foci induced by YTHDF2 overexpression were reversed after ETV5 was downregulated." (PMID 38247171, 2024). "Mechanistically, METTL3 inhibition triggers an interferon response within tumour cells, amplifying the anti‐tumour immune response, along with deletion of the m6A reader protein YTHDF2 in tumours inhibiting major histocompatibility complex (MHC)‐I degradation." (PMID 39568154, 2024). "In papillary thyroid carcinoma (PTC), METTL3 is able to cooperate with YTHDF2 to inhibit IL-8 secretion, reduce tumor-associated neutrophil (TAN) recruitment, and inhibit tumor growth using c-Rel and RelA as downstream modification targets." (PMID 39072324, 2024). "The absence of YTHDF2 in Tregs promotes Treg cell apoptosis and inhibits tumor progression via the YTHDF2-m6A-NF-κB pathway." (PMID 39726589, 2024). "Kazuo Tsuchiya's research in NSCLC found that knocking out YTHDF1 and YTHDF2 elevated PD‐L1 expression in tumours and changed several immune‐related genes." (PMID 39135292, 2024). "From the results of CRISPR‐Cas9‐mediated YTHs protein KO B16 mouse tumour model, we discovered YTHDF2 deletion had a notable inhibition of tumour growth through T‐cell immune system." (PMID 39568154, 2024).
tumor (continued). "The volume and proliferation activity of tumor nodules, as well as lung metastatic foci, were significantly higher in mice that were injected with Hepa1‐6 cells overexpressing YTHDF2." (PMID 38247171, 2024). "Recent studies on the small molecule inhibitor DC‐Y13‐27, targeting YTHDF2, indicate it can enhance tumour response to radiotherapy and immunotherapy, providing a novel therapeutic strategy for cancer treatment." (PMID 39135292, 2024). "YTHDF2 is highly expressed in PCa and correlates with poor prognosis, while miR-493-3p inhibits its expression, restraining tumor malignancy." (PMID 38798700, 2024). "YTHDF2 has also been identified as an independent translation regulatory factor for m6A-modified mRNA, promoting tumor growth by facilitating the translation of 6PGD mRNA." (PMID 38365891, 2024). "IGF2BP1, HNRNPA2B1, FTO, WTAP promote the EC progression, but METTL3, METTL14, YTHDF2 work as tumor suppressors in EC." (PMID 39582531, 2024). "On the other hand, other studies suggest YTHDF2 is downregulated in GC and functions as a tumor suppressor." (PMID 39342406, 2024). "Recently researches have indicated that molecules involved in m6A methylation modification, such as METTL3 and YTHDF2, play an important role in promoting the anti-tumor activity of NK cells." (PMID 39439794, 2024). "In thyroid cancer, high expression of METTL3 in tumor cells inhibits the demethylation of CD70mRNA, maintains the degradation of transcripts mediated by YTHDF2, thereby releasing T cells from suppression and enhancing the efficacy of PD-1 blockade." (PMID 39372415, 2024). "The results demonstrated that knocking down YTHDF2 resulted in a dramatic retardation of tumor growth and weight." (PMID 39593172, 2024). "For instance, in lung cancer, ALKBH5 counteracts YTHDF2-mediated degradation of Sox2 and thereby promoting tumor aggressiveness." (PMID 39098905, 2024). "Taken together, these findings suggest that METTL3 and YTHDF2 are both crucial for anti‐tumour immunity, and YTHDF2 probably functions as a downstream executed reader of the tumour‐killing effect of STM2457 treatment." (PMID 39568154, 2024). "In response to various stimuli such as tumor cells and infections, the expression of YTHDF2 increases in NK cells." (PMID 39072324, 2024). "In conclusion, the results demonstrated that YTHDF2 significantly accelerated tumor growth and metastasis in vivo." (PMID 39593172, 2024). "The overall effects of “degradation and translation conflicts” caused by YTHDF2 resulted in the elevated protein expression of ETV5 and promoted tumor progression." (PMID 38247171, 2024). "According to research by Xu's group, decreasing YTHDF2 increases LATS1's ability to limit tumour growth while high YTHDF2 expression in BRCA cells encourages the creation of tumours." (PMID 39135292, 2024). "YTHDF2 is also upregulated in prostate cancer and alters the tumor proliferation and migration using miR-493-3p." (PMID 39457524, 2024). "Recent reports have mentioned that YTHDF2 can degrade tumor promoter and tumor suppressor gene mRNA and have a dual role in tumor progression." (PMID 39054967, 2024). "Numerous reports have suggested that YTHDF2 can impact cancer progression by affecting the tumor stemness during carcinogenesis." (PMID 38776708, 2024). "The study conducted by Zhang and colleagues demonstrates that deletion of YTHDF2 in regulatory Tregs diminishes tumor growth, increases Treg apoptosis, and impairs the function of TME in murine models." (PMID 39199429, 2024). "Studies have shown that the loss of YTHDF2 in Tregs promotes Treg apoptosis and suppresses their function in the TME, thereby inhibiting tumor progression through the YTHDF2-m6A-NF-κB pathway." (PMID 38902779, 2024).